JMJD1C (jumonji domain containing 1C)
Diseases named in the same sentence as JMJD1C in open-access papers (continued):
Sharing a sentence is not in itself a finding about the gene and the disease.
cancer (19 papers, 2016 to 2025). A tumor composed of atypical neoplastic, often pleomorphic cells that invade other tissues. "JMJD1C/B are epigenetic regulators, that control a variety of biological functions in normal tissues and tumors and their inhibition by methylstat likely interferes with additional cancer associated pathways and DNA-repair routes, awaiting further investigation." (PMID 39915607, 2025). "In agreement with these previous studies in cancers, we observed the proliferative and antiapoptotic role of JMJD1C in PASMCs exposed to hypoxia." (PMID 36934091, 2023). "We focused on JMJD1C, a histone lysine demethylase, as histone lysine methylation and demethylation have recently emerged as important regulatory steps in cancer." (PMID 37491298, 2023). "It has been documented that JMJD1C drives the proliferation, migration, and invasion in a variety of cancers." (PMID 36934091, 2023). "JMJD1C was reported to function as a tumor facilitator in some cancers by promoting cancer proliferation and inhibiting apoptosis." (PMID 34022910, 2021). "Jumonji domain containing 1C (JMJD1C) has been identified as a DNA-damage response (DDR) component to regulate the cellular behaviors of cancer cells." (PMID 34022910, 2021). "Since super-enhancers (SEs) have been shown to drive high levels of oncogenic gene expression to maintain cancer cell survival, we next set out to determine whether JMJD1C and RUNX1 regulate gene expression by binding to SEs." (PMID 39450904, 2025). "However, several contradictory studies have shown an antiproliferative effect of JMJD1C on cancer cells." (PMID 36934091, 2023). "One of the tested and verified alternatively spliced candidates, JMJD1C, is a histone demethylase that regulates DNA double‐strand break repair and is involved in tumorigenesis, linking ARID1A once more to cancer." (PMID 40170512, 2025). "On the other hand, in transcriptional misregulation in the cancer signaling pathway, only MYCN expression was notably decreased, and the expression of 20 genes, including GADD45A, CXCL8, JMJD1C, RUNX1, and H3C14, was significantly increased in NHEKs upon HPV8 E7 expression." (PMID 35665406, 2022). "Concerning histone demethylases, Jumonji C domain KDMs members of family GASC1/KDM4C and JMJD1C/KDM3C demethylating agents of repressive histone marker H3K9 and KDM7B/PHF8 which specifically demethylate H3K27me1/2, play a critical role in ESCC cancer development." (PMID 31739546, 2019). "In our study, JMJD1C was solely found in benign tumors, not in any cancers or normal tissues, probably indicating a potential role of JMJD1C as a biomarker for benign tumors of the oral cavity in dogs." (PMID 30001383, 2018). "However, insufficient depletion of JMJD1C might explain the negative dependency data on JMJD1C depletion in all cancer cell lines shown on Depmap." (PMID 39450904, 2025).
tumor (19 papers, 2013 to 2025). "From the most mutated genes, CREBBP and JMJD1C especially were more commonly mutated in the breast NET cohort compared with the IDC cohort." (PMID 36085291, 2022). "In addition, in vivo experiments revealed that circ_0006168 deficiency suppressed tumor growth by increasing miR-194-5p and decreasing JMJD1C, implying that circ_0006168 silence might improve Taxol sensitivity in vivo." (PMID 34022910, 2021). "For Treg cells, researchers have found that the tumor microenvironment significantly induces high expression of histone demethylase JMJD1C in tumor Tregs." (PMID 39136031, 2024). "The use of JMJD1C inhibitors significantly inhibits tumor growth and has good application prospects." (PMID 39136031, 2024). "Immunohistochemistry (IHC) staining for BTBD16, EpCAM, FOXM1, AGXT and JMJD1C was carried out in normal and tumor thyroid tissue samples (three patient biopsies available), belonging to two NMTC families: NMTC_1 and NMTC_4." (PMID 37175550, 2023). "JMJD1C facilitates tumor growth in various malignancies by promoting cancer cell growth and preventing apoptosis." (PMID 37384299, 2023). "A study demonstrated that inhibiting circ_0006168 decreased tumor growth in vivo by sponging miR-194-5p and modulating JMJD1C, and in vitro by reducing cell proliferation, invasion, and migration, and Taxol-resistant ESCC apoptosis." (PMID 37384299, 2023). "The impact of SOX9 and JMJD1C depletion on OS tumor growth was examined in vivo using xenografts and immunohistochemistry." (PMID 37491298, 2023). "Overexpression of JMJD1C inhibited tumor growth, but this effect was reversed by the addition of sh‐SOCS2 treatment." (PMID 34586733, 2021). "In conclusion, interference of circ_0006168 restrained cell proliferation, invasion and migration and accelerated apoptosis of Taxol-resistant cells in vitro, and inhibited tumor growth in vivo via sponging miR-194-5p and regulating JMJD1C." (PMID 34022910, 2021). "Jmjd1c was identified as a co-activator of the tumor-inducing fusion gene AML1-ETO and shown to be recruited by AML1-ETO to target gene promoters where it lowers the levels of the repressive mark H3K9me249." (PMID 31209209, 2019). "Inhibiting JMJD1C expression does not affect the development and function of peripheral Tregs but reduces tumor-associated Tregs, consequently slowing tumor growth." (PMID 39136031, 2024). "Although phosphodiesterase type 5 (PDE5) was reportedly responsible for the effect of tadalafil against tumors, tadalafil may also confer tumor repression by targeting JMJD1C/JMJD1B." (PMID 33289299, 2021). "It was observed that overexpression of JMJD1C resulted in inhibition of tumor growth." (PMID 34586733, 2021). "Moreover, the expression levels of circ_0006168, miR-194-5p and JMJD1C were measured in tumor tissues." (PMID 34022910, 2021). "Therefore, we suppose that JMJD1C may be an essential controller of macrophage polarization serving to regulate inflammatory responses targeting the tumor." (PMID 34586733, 2021). "We further analyzed the expression profiles of JMJD1C and RUNX1 across various tumor types using the TCGA database." (PMID 39450904, 2025). "Then CD86 (M1 macrophage marker) and CD206 (M2 macrophage marker) were determined using flow cytometry, which showed that overexpression of JMJD1C resulted in a decrease of CD206+ cells and an increase of CD86+ cells in tumor tissues." (PMID 34586733, 2021). "Moreover, we discovered that JMJD1C, a chromatin factor, is a novel binding partner of SOX9, and depletion of JMJD1C impairs OS tumor growth." (PMID 37491298, 2023). "Last, JMJD1C knockdown and SOX9 knockdown phenocopy in the inhibition of OS tumor growth." (PMID 37491298, 2023).
hematologic malignancies (1 paper, 2020). "Some of these hub genes were either considered essential to the survival of AML cells (JMJD1C) or identified as fusion partners (CHD1) of the major player in hematologic malignancies (RUNX1)." (PMID 31988326, 2020).
metabolic disease (1 paper, 2021). A congenital disorder (due to inherited enzyme abnormality) or acquired (due to failure of a metabolically important organ) disorder resulting from an abnormal metabolic process. "Single-nucleotide polymorphism in JMJD1C is connected to the progression of T2DM, indicating the potential involvement of JMJD1C in the development of metabolic diseases as evaluated by genome-wide association studies." (PMID 35087408, 2021).
JMJD1C also shares sentences with these, for which no sentence is quoted: myeloproliferative neoplasm (4 papers); esophageal cancer (3); Alzheimer disease (2); myeloid leukemia (2); rheumatoid arthritis (2); age (1); atherosclerosis (1); atransferrinemia (1); benign tumors (1); bipolar disorder (1); breast (1); colon cancer (1); depression (1); DiGeorge syndrome (1); ependymoma (1); heart failure (1); hemochromatosis (1); hepatocellular carcinoma (1); Huntington disease (1); liver cancer (1); meningioma (1); neurological disorders (1); ovarian teratoma (1); pancreatic cancer (1); sarcopenia (1); schizophrenia (1); thrombosis (1); viral infection (1).